IL33 (interleukin 33)
Diseases named in the same sentence as IL33 in open-access papers (continued):
Sharing a sentence is not in itself a finding about the gene and the disease.
asthma (continued). "MMP-9 is a downstream target of IL-33,16 and activity is increased in sputum from patients with severe asthma who are unresponsive to steroid therapy." (PMID 25746970, 2015). "IL-33 is important in fungus-induced asthma exacerbations, but its role in fungal sensitization is unexplored." (PMID 25746970, 2015). "IL-33 plays significant roles in the pathogenesis of asthma, and IL-13 can be induced by IL-33 via ST2 signaling." (PMID 26610488, 2015). "So in line with these findings it is likely that also anti IL-33 treatment will be safe and serve as a successful therapy against several inflammatory conditions, including severe asthma and atopic dermatitis." (PMID 26214807, 2015). "Quantitative IL-33 expression in ASM correlated with AHR in those with asthma (r = −0.52, P = 0.007)." (PMID 25683166, 2015). "A recent study showed that IL‐33 and type 2 cytokines are induced during RV‐induced asthma exacerbations 38, suggesting that RV plays a key role in amplifying type 2 inflammation." (PMID 26734461, 2015). "The strong Th2-promoting ability of IL-33-activated ILC2s has been largely demonstrated in animal models of Th2 disease such as asthma and helminth infection." (PMID 26473724, 2015). "IL-33 positively induces Th2-type responses, and the proinflammatory role of IL-33 has been verified in Th2 cell-mediated inflammatory diseases, such as asthma." (PMID 24733959, 2014). "Dexamethasone fails to abolish TNF-α-induced IL-33 upregulation in airway smooth muscle cells, which are a major source of IL-33 in asthma." (PMID 24822215, 2014). "It has been shown that epithelial cell damage caused by a number of chemicals or viral exposure significantly contributed to the increased allergic responses and asthma pathogenesis through the expression of alarmins such as IL-33 and TSLP." (PMID 25202911, 2014). "We and others have previously reported that the HDM-driven model of asthma depends on the activity of IL-33 and is driven by antigen-presenting DCs." (PMID 24453940, 2014). "Recently emerging evidence has shown that IL-33 is also a potent inducer of pro-inflammatory cytokines and chemokines by mast cells, resulting in the development or exacerbation of asthma or atopic allergy and anaphylaxis." (PMID 24586149, 2014). "IL33 encodes a cytokine belonging to the IL1 superfamily, and is the natural ligand for the IL1RL1 receptor, which has been previously implicated in asthma, inflammation, and a number of immune disorders." (PMID 24779919, 2014). "Genome-wide association (GWA) studies on asthma have suggested that several polymorphisms in several genes, including ORMDL3-GSDMB, DENND1B, HLA-DP, SLC30A8, IL1RL1-IL18R1, IL33, SMAD3, TSLP, and NOTCH4 are associated with asthma." (PMID 23861779, 2013). "IL-13 and IL-33 are known to drive eosinophil maturation and infiltration, mucus production and bronchial hyperreactivity." (PMID 23738146, 2013). "For example, IL-33 has been reported to enhance the asthma phenotype induced by exposure to a Th2 antigen, however, by signaling through its receptor, ST2-IL1RL1, IL-33 has been shown to have significant protective function in the left heart." (PMID 23383100, 2013). "Previously, high levels of IL33 have been observed in the bronchial epithelium from patients with asthma when compared with healthy controls." (PMID 24282527, 2013). "In this section, we review the significant roles of IL-25 and IL-33 and their main responder cells, ILCs2, in airway allergic diseases and asthma." (PMID 23209480, 2012). "Several studies indicated ILCs2 in allergic reactions and asthma as major responders to IL-25 and IL-33 and significant inducers of type 2 responses." (PMID 23209480, 2012). "Expression of IL-33 is highly up-regulated in the lungs of asthmatic patients and in mouse models of asthma." (PMID 23087690, 2012).
asthma (continued). "A GWA study of eosinophil counts with follow-up testing in asthma case-control studies identified variants near IL1RL1/IL18R1 and IL33 as being associated with asthma." (PMID 23028483, 2012). "They observed associations with asthma, particularly childhood-onset asthma, at multiple loci (ORMDL3/GSDMB, IL1RL1/IL18R1, HLA-DQ, IL33, SMAD3, and IL2RB)." (PMID 23028483, 2012). "Results of these studies demonstrated that IL-33 increases in clinical and experimental models of asthma so that its levels correlate with disease severity and that IL-33 and/or ST2 blockage reduce symptom severity." (PMID 23209480, 2012). "IL-33 strongly induces Th2 cytokine production from these cells and can promote the pathogenesis of Th2-related disease such as asthma, atopic dermatitis and anaphylaxis." (PMID 21871091, 2011). "Given that IL-33 is a strong inducer of Th2 immune responses its role in asthma has been extensively studied." (PMID 21871091, 2011). "The IL-33 expression was particularly evident in those with severe asthma, and the expression was mainly located in bronchial epithelial cells." (PMID 21871091, 2011). "The mRNA and/or protein levels of ST2, soluble ST2, which acts as a decoy receptor for IL-33, and IL-33 are increased in specimens from patients with allergic diseases such as asthma, conjunctivitis, rhinitis and atopic dermatitis." (PMID 21494550, 2011). "Several animal model studies have highlighted a functionally important role for IL-33/ST2 in asthma and allergic airways inflammation." (PMID 21871091, 2011). "IL-33 expression increases in bronchial biopsies in asthmatic subjects compared to controls, as well as subjects with severe asthma." (PMID 20671916, 2010). "IL-33 is a recently characterized IL-1 family cytokine and found to be expressed in inflammatory diseases, including severe asthma and inflammatory bowl disease." (PMID 20689814, 2010). "This is despite mounting evidence for IL-33 expression in type 2 inflammatory diseases, including severe asthma, allergic conjunctivitis and inflammatory bowel disease." (PMID 20689814, 2010). "In a murine model of asthma, pretreatment with sST2 reduces IL-4, IL-5, and IL-13 production from IL-33-stimulated splenocytes." (PMID 20671916, 2010). "IL33 amplification of IL13-induced alternatively-activated macrophage polarization in asthma patients has also recently been suggested." (PMID 20625511, 2010). "This was confirmed in an animal model where introduction of soluble IL1RL1 decreased pro-inflammatory cytokine (IL4, IL5 and IL13) production in a murine asthma model after treatment with IL33." (PMID 21629437, 2010). "The clinical trial findings of itepekimab, an anti‐IL‐33 monoclonal antibody, currently demonstrate a significant reduction in blood eosinophil levels and improvement in lung function among patients with moderate to severe asthma." (PMID 41568067, 2026). "In such a study, increased production of IL-33 and TSLP was linked to increased asthma severity." (PMID 40869013, 2025). "Furthermore, the IL-33 and A. alternata-challenged asthma mouse model has demonstrated that TNF-α/TNFR2 signaling is crucial for ILC2s survival and function and induction of AHR." (PMID 40236701, 2025). "Interestingly, a study has demonstrated that some asthma patients can selectively produce natural anti-IL-33 autoantibodies in their serum." (PMID 39925809, 2025). "Finally, IL1LR1, which plays a central role in allergic inflammation and asthma as a key receptor for IL33, was upregulated following combined exposure to TM and microbial components." (PMID 41368042, 2025). "Background/Objectives: Interleukin-33 (IL-33) is crucial in immune-mediated diseases like asthma." (PMID 41012490, 2025). "IL-33 is highly expressed in skin or airway epithelial cells of AD or asthma animal models." (PMID 40236701, 2025).
asthma (continued). "Asthma is characterized by a Th2-mediated immune response, which plays a key role in the pathogenesis of allergic airway inflammation by secreting Th2 cytokines such as IL-33, IL-5, and IL-13." (PMID 40422811, 2025). "IL-33, a member of the IL-1 cytokine family, is released upon cell damage or stress and acts as an alarmin, initiating inflammation and contributing to allergic diseases and asthma." (PMID 40981017, 2025). "Studies have demonstrated that inflammatory characteristics of asthma may be related to the release of Th2 cytokines (IL-4, IL-5, IL-13 and IL-33) mediated by the regulation of arachidonic acid metabolic pathway." (PMID 40771395, 2025). "Itepekimab and astegolimab are two anti-IL-33 antibodies that could have a role in the future treatment of severe asthma." (PMID 40364184, 2025). "IL-33-deficient mice also exhibited attenuated eosinophilic pulmonary inflammation in a protease-induced asthma model, which was independent of T and B cells." (PMID 39962262, 2025). "Indeed, targeting the IL‐33 signaling pathway using blocking antibodies ameliorated exacerbation symptom severity in mouse models of type 2‐high asthma." (PMID 40016948, 2025). "The IL-33/ST2 pathway is linked to asthma susceptibility, with inhaled allergens, respiratory viruses, and pollutants triggering IL-33 release and exacerbating asthma." (PMID 39925809, 2025). "In individuals with low blood eosinophil levels, this medication, which targets the IL-33 pathway, resulted in a marginally better reduction in exacerbation; this suggests that the IL-33 pathway may be more significant in type 2 low severe asthma." (PMID 40136649, 2025). "A Phase 2 trial evaluated the efficacy of itepekimab, an IL-33-targeting therapy, in asthma." (PMID 40305320, 2025). "IL-33 may promote the exacerbation of virus-induced asthma by enhancing type 2 inflammation or by attenuating innate and adaptive Th1-like and cytotoxic responses." (PMID 40636260, 2025). "Indeed, targeting alarmins during asthma has shown great potential, with a range of novel biologics currently in clinical trials for asthma, such as itepekimab targeting IL‐33, astegolimab targeting IL‐33 receptor ST2, or tezepelumab targeting TSLP." (PMID 39991870, 2025). "Another biologic in development may treat T2-high and T2-low asthma: astegolimab, a human monoclonal antibody that suppresses IL-33 signaling by targeting its receptor, ST2." (PMID 40486460, 2025). "IL33 is an alarmin which is involved in the activation of immune cells important in Th2 responses and allergic inflammation, and the IL33/IL1LR1 axis is critical in susceptibility to asthma." (PMID 41368042, 2025). "Furthermore, IFN-λ can limit the decrease TSLP and IL-33 production, providing evidence for a protective role in asthma exacerbations." (PMID 40636260, 2025). "In addition, blocking the IL-33/ST2 signaling pathway effectively inhibits the occurrence of asthma in asthmatic mice." (PMID 39925809, 2025). "For example, periostin and DPP-4 are being explored as potential predictors for IL-13-targeting biologics in asthma, while IL-33 and soluble IL-33R levels in sputum or serum may aid in selecting therapies that inhibit IL-33 signaling." (PMID 40004611, 2025). "Consistently, human serum IL-33 levels are correlated with clinical asthma and AD severity." (PMID 39962262, 2025). "This phenomenon is reflected in the differential extracellular vesicle (EV) proteome in bronchial wash from COPD and asthma samples, which could mark disease activity and potentiate IL-33 function." (PMID 40553562, 2025). "A recent study found that inflammation of the airway was decreased in IL-33−/− asthma mouse models, further supporting the hypothesis that this particular alarmin is connected to the pathogenesis of asthma." (PMID 40723867, 2025). "Levels of anti-IL-33 antibody are greater in patients with asthma compared to healthy volunteers." (PMID 40723867, 2025).
asthma (continued). "Recent studies have demonstrated that type 2 inflammation and indirect airway hyperresponsiveness in asthma are related to a shift in mast cells from the submucosa to the airway epithelium and that mast cells cooperate with epithelial cells through IL‐33 signaling to regulate type 2 inflammation." (PMID 40131162, 2025). "From these findings, SLPI may be involved in the pathogenesis of protease-mediated Th2-type inflammation, exemplified by asthma, by modulating the innate immune response, principally through attenuation of IL-33 production." (PMID 40546642, 2025). "In contrast, increased sST2 in females may interfere with the chemoattractant function of IL‐33, resulting in fewer airway ILC2s in females with asthma compared with males." (PMID 40022441, 2025). "Moreover, the addition of metformin to IL-33 reduced the presence of IL-13 and IL-5, thus suggesting the relationship between the long-known biguanide and alarmins in asthma." (PMID 40723867, 2025). "These new findings may facilitate the identification of patients more (or less) amenable to IL33/IL1RL1 blocking strategies targeting this pathway for clinical benefit in asthma." (PMID 39301832, 2024). "Similarly, the activation of TLR4 by cockroach allergens results in the release of TSLP, IL-25, and IL-33, further contributing to the inflammatory environment characteristic of asthma." (PMID 39457624, 2024). "The children with asthma had an inflammatory profile that was characterized by increased levels of several pro-inflammatory cytokines, including IL-2, IL-5, IL-13, IL-17A, IL-22, IL-33, TNF-α, and reduced level of anti-inflammatory cytokine, IL-10." (PMID 39902293, 2024). "Interestingly, in this study, the E06-induced reduction of both TNF and IFN-γ correlates with a trend for IL-33 reduction, suggesting unique effects of OxPCs in asthma pathophysiology." (PMID 39194564, 2024). "The immunopathophysiology of allergic conjunctivitis is similar to that of asthma and allergic rhinitis because Th2-derived cytokines, Th9-derived cytokine, IL-33, and TSLP induce the type 2 allergic immune-mediated inflammatory processes in these allergic diseases." (PMID 38541674, 2024). "While TSLP, IL-25, and IL-33 are acknowledged as the key promoters of the T2-skewed inflammatory response in asthmatic airways, there is increasing evidence for the role of additional epithelial-derived cytokines in asthma pathology." (PMID 39457624, 2024). "Truncated spliced IL33 transcripts have also been cloned from human cell lines, asthma endobronchial biopsy samples, and primary COPD airway basal cells, but the mechanism by which these alternatively spliced forms are produced is also unknown." (PMID 38456508, 2024). "Additionally, it is important to note that there remain areas that require further research, including the precise role of IL-25 in severe asthma and investigating the long-term effects of IL-33 inhibitors." (PMID 39457624, 2024). "The modest aggregate clinical effects seen in the current study with PF-06817024 are consistent with results from clinical trials with other IL-33 inhibitors such as itepekimab and etokimab; however, these trials were conducted in patients with asthma and AD, respectively." (PMID 39215351, 2024). "European children possessing the asthma risk allele at either rs1888909 or rs992969 showed higher levels of IL-33 protein in comparison to children who did not carry these alleles." (PMID 38731070, 2024). "These immunological markers may correspond to pathophysiological characteristics of asthma: periostin, IgE, IL-5, and IL-33 for T2 asthma; IL-6, IL-8, IL-17A, and IL-33 for non-T2 asthma." (PMID 38256660, 2024). "Additionally, a phase 2 trial of itepekimab, a monoclonal against IL-33, reported lower frequency of asthma exacerbation." (PMID 39200943, 2024).
asthma (continued). "The concomitant increase in expression of IL-33 induces T2 cytokines production in MCs, potentially amplifying T2-mediated airway inflammation and contributing to the persistent exacerbation of severe asthma." (PMID 39707175, 2024). "The epithelial cell-derived danger signal mediators interleukin-33 (IL-33) and thymic stromal lymphopoietin (TSLP) have emerged as key players in the intricate network of adaptive Th2 immune responses associated with asthma." (PMID 38731070, 2024). "The question is whether asthma risk is modified by the combined effects of TSLP and IL-33 genotypes and whether it is correlated with atopy." (PMID 38731070, 2024). "In addition, obesity and asthma showed a significant interaction effect on the plasma levels of IL-5, IL-10, IL-17A, IL-33, TNF-α, and leptin." (PMID 39902293, 2024). "Type 2 inflammation is a common feature in patients with asthma, characterized by the activation of group ILC2s in the lungs in response to inhaled allergens, particularly through the production of alarmins such as IL-33 by epithelial cells." (PMID 39301028, 2024). "IL-33 not only induces antiviral signaling in mast cells (MCs) but also upregulates receptors for human rhinoviruses (HRVs), potentially enhancing viral infection and contributing to viral-induced asthma exacerbation." (PMID 39301028, 2024). "IL-33 is an important marker of severe and steroid-refractory asthma." (PMID 39194564, 2024). "Interestingly, another study established that IL-33 in particular played a critical role in driving viral-induced asthma exacerbations, an effect that was attenuated by inhibiting IL-33’s receptor, ST2." (PMID 39457624, 2024). "Epithelial cell-derived cytokines, such as interleukin (IL)-25 and IL-33, are capable of stimulating ILC2s to produce T-helper (Th) type 2 cytokines, including IL-4, IL-5 and IL-13, thereby facilitating the pathogenesis of asthma." (PMID 38650035, 2024). "Asthma is a significant health concern, and innovative studies targeting IL-33 could potentially lead to effective treatments for asthma patients." (PMID 39301028, 2024). "This highlights the potential of the IL-33/IL1RL1 axis in modulating IBD susceptibility and the shared inflammatory pathways between IBD and respiratory diseases like asthma, suggesting personalized treatment options for IBD patients resistant to certain therapies." (PMID 39144148, 2024). "In summary, cytokines such as IL-33 play a critical role in the inflammatory response observed in asthmatic patients, particularly contributing to the enhanced type 2 (T2) inflammatory response seen during the aggravation state of asthma." (PMID 39301028, 2024). "Serum IL-33 levels were also assessed in a comparison of subjects with allergic asthma and nonallergic asthma, where IL-33 showed a positive association with allergic asthma." (PMID 39171751, 2024). "For treatment of allergic diseases such as asthma, IL-33 blockade is advantageous." (PMID 38890291, 2024). "It has been discovered that the IL-33/ST2 pathway plays a significant role in asthma." (PMID 38650035, 2024). "For asthma, several drugs targeting the IL-33/ST2 pathway are under clinical development." (PMID 38082335, 2023). "The mechanism underlying the contribution of IL‐33 and ILC2s to asthma exacerbation has not yet been established in patients with EA." (PMID 37357549, 2023). "Moreover, biologics targeting IL-33 and its receptors, which are itepekimab and astegolimab, respectively, have also shown clinical benefits in asthma treatment." (PMID 37371472, 2023). "Associations between IL‐33 and IL1RL1 genetic variants have been reported for asthma." (PMID 35986608, 2023). "In addition, anti-IL-33 has been shown to inhibit neutrophilic inflammation in animal models of asthma." (PMID 38283037, 2023). "In this regard, a clinical trial has shown that IL-33 targeting could efficiently reduce exacerbations in patients with severe asthma." (PMID 37153601, 2023).